IPO7 (importin 7)
Diseases named in the same sentence as IPO7 in open-access papers (continued):
Sharing a sentence is not in itself a finding about the gene and the disease.
cancer (22 papers, 2002 to 2025). A tumor composed of atypical neoplastic, often pleomorphic cells that invade other tissues. "Using LC-MS/MS proteomics, we found a novel interaction between TMCO1 and nuclear transport proteins, including KPNB1 and IPO7, which are associated with several cancers." (PMID 39353922, 2024). "Focusing on the nervous system disorders, ARF3 presented a higher association score, and it was related to more diseases than IPO7, which was more related to measurement, cancer, and gastrointestinal diseases." (PMID 35742897, 2022). "Additionally, IPO7 is observed to be overexpressed in diverse cancers, and it is implicated in promoting cancer progression." (PMID 35588577, 2022). "Knockdown of Importin-7 synergizes with enzalutamide to induce cycle arrest and promote cancer cell growth inhibition." (PMID 37391429, 2023). "Mechanistically, the knockdown of Importin-7 induces G0/G1 arrest of the cell cycle by upregulating the expression of cycle repressors, including p21 and p27, thereby suppressing cancer growth and malignant progression." (PMID 37391429, 2023). "IPO7 knockdown reduces survival advantages of cancer cells by downregulating and upregulating AKT and BAX levels, respectively." (PMID 34575983, 2021). "Materials and Methods: TCGA and GEO datasets were used to identify dysregulated expression of IPO7 in various cancers." (PMID 34650978, 2021). "Knocking down IPO7 remarkably suppressed cancer cell proliferation and metastasis, while it promoted apoptosis." (PMID 34660566, 2021). "Since several studies showed that curcumin exerts its anti-cancer effect by regulating the expression of microRNAs (miRs), we utilized miR target prediction software miRSearch V3.0 to determine if IPO7 is subject to regulation by miRs." (PMID 30045750, 2018). "We first confirmed that the knockdown of Importin-7 could enhance the growth inhibition of cancer cells by enzalutamide using CCK8 assay and EdU staining assay." (PMID 37391429, 2023). "Increasing investigations have shown that Importin-7 universally exists in various cancers." (PMID 37391429, 2023). "IPO7 expression was remarkably elevated in the cancer tissues of PC patients." (PMID 35588577, 2022). "As a member of the importins, aberrant expression of the IPO7 gene has been recently reported in a multitude of malignancies and is correlated with tumorigenesis and aggressiveness, and IPO7 has evolved as a potential cancer therapeutic intervention target." (PMID 34650978, 2021). "Meanwhile, high expression of IPO7 was correlated with of poorer prognosis for cancer patients." (PMID 34650978, 2021). "Additionally, the translocation of mothers against decapentaplegic homolog (SMAD) family members, a class of proteins that are crucial regulators in cancer biology, from the cytoplasm to the nucleus, is also regulated by IPO7." (PMID 34660566, 2021). "Notably, IPO7 is frequently overexpressed in cancers, and it facilitates the progression of multiple types of cancers." (PMID 34660566, 2021).
cancer (continued). "To explore the potential oncogenic role of IPO7, we first applied the TCGA and GTEx datasets to analyze and results showed that the gene expression of IPO7 was significantly increased in the various cancers." (PMID 34650978, 2021). "Furthermore, Chijongdan repressed the expression of ribosome biogenesis related proteins such as UBF, Fibrillarin, NPM, and IPO7, indicating that Chijongdan can inhibit the rDNA transcription or processing of rRNA during cancer progression of A549 cells." (PMID 25345917, 2014). "Here, we used a slightly different approach, monitoring cell viability following depletion of RADIL and IPO7 in KRAS mutant, KRAS WT, and normal human cancer cell lines." (PMID 35839996, 2022). "Of the eight modeling RBPs, half were upregulated including PABPC1, PRPF6, OAS1, IPO7, and half were downregulated including RBM5, RBM6, LSM12, and FXR7 in cancer cases." (PMID 33584809, 2020). "Others have cancer-relevant functions, such as steroid hormone synthesis (HSD17B8, earlier), and covalent modification of histones (HUWE1, IPO7, MLL4, PAXIP1, PRKAA2, all later except PAXIP1)." (PMID 23762276, 2013). "Activating genes in this branch, first of all TERT, heat shock protein 90 (HSP90AA1, HSP90AB1), importin 7 (IPO7) and p23 (PTGES3) are overexpressed in cancer, while the heat shock protein 70 (HSPA1A) and CHIP ubiquitin ligase (STUB1), both acting as suppressors, are underexpressed." (PMID 31750255, 2019). "Our study, for the first time, suggests the miR-22/IPO7/HIF-1α axis as new molecular target of curcumin, revealing innovative therapeutic implications of this natural compound for treatment of CML as well as of other cancer types in which HIF-1α has a prominent role." (PMID 30045750, 2018). "RADIL and IPO7 depletion, relative to the luciferase control knockdown, significantly reduced cell viability of cell lines harboring the mutant or WT KRAS, suggesting that these genes are important, but disrupting them does not produce specific toxicity in KRAS mutant cancer cells." (PMID 35839996, 2022).
tumor (18 papers, 2002 to 2025). "IPO7 is implicated in several human malignancies by facilitating the nuclear import of oncogenes to support tumor cell growth, migration, and metastasis." (PMID 40565276, 2025). "As one of the candidates, the knockdown of Importin-7 showed a significant tumor-suppressing effect." (PMID 37391429, 2023). "In conclusion, this work confirms that IPO7 can enhance the malignant biological behaviors of PC cells through positive regulation of the ERBB pathway and is implicated in facilitating tumor growth and lung metastasis." (PMID 35588577, 2022). "In nude mice tumorigenicity assay, it was revealed that the tumor volume was remarkably reduced after the knockdown of IPO7 relative to the control group." (PMID 35588577, 2022). "It was observed that the average tumor size in the IPO7 knockdown group was significantly lower compared with that in the control group." (PMID 34660566, 2021). "Subcutaneous xenograft transplanted tumor model and caudal vein injection model in mice were also established to validate the oncogenic role of IPO7." (PMID 34660566, 2021). "HPAC cells with stable IPO7 knockdown and the cells in the control group were inoculated into nude mice, respectively, and the tumor growth was measured." (PMID 34660566, 2021). "To further explore the impact of IPO7 in the tumor immune microenvironment, we first quantified the correlation of IPO7 and the infiltration levels of the immune cell types in CC samples by the TIMER database." (PMID 34650978, 2021). "Our work also shows that the expression of IPO7 negatively correlates with CD8+ T cell infiltration via regulating CD276 in CC which is a key immune checkpoint in tumor immunotherapy." (PMID 34650978, 2021). "The IPO7 protein appeared to be highly expressed in the cytoplasm and nuclei of tumor cells." (PMID 40565276, 2025). "•Knockdown of IPO7 inhibited tumor growth and lung metastasis in vivo." (PMID 35588577, 2022). "The CPTAC dataset also showed a higher level of IPO7 protein in the various primary tumor tissues." (PMID 34650978, 2021). "As expected, overexpression of IPO7 promoted the tumor growth." (PMID 34650978, 2021). "Additionally, IPO7 could positively modulate the ERBB2, and knockdown of IPO7 inhibited tumor growth and lung metastasis in vivo." (PMID 35588577, 2022). "In addition, knockdown of IPO7 inhibited tumor growth and lung metastasis in vivo." (PMID 35588577, 2022). "Taken together, IPO7 may contribute to regulating the tumor immune microenvironment of CC." (PMID 34650978, 2021). "Interestingly, elevated levels of importin 7 transcripts were found in various tumor cells, suggesting that the nuclear transport pathway of hTERT might be a potential target for future drug development." (PMID 24586428, 2014). "The data of qRT-PCR showed that IPO7 and ERBB2 expression were remarkably down-modulated in the tumor tissues of IPO7 knockdown group." (PMID 35588577, 2022). "Additionally, IPO7 knockdown reduced the expression of MALAT1 and N-cadherin in the tumor tissues but increased the expression of miR-129-5p and E-cadherin." (PMID 34660566, 2021). "Following this second hypothesis, we computationally found reliable interactions between UCA1 and the 3′-UTRs of ANLN, BIRC5, IPO7, KIF2A, and KIF23 that overlapped several miRNA-binding sites of tumor-suppressor miRNAs." (PMID 30195762, 2018).
tumor (continued). "Therefore, this study was the first proposed the relationship between ABCB6, IPO7, TIMM9, and ACAT1 and HBV, and they may be related to tumor progression in HBV-induced HCC as FZD7." (PMID 36685852, 2022). "In the present study, we found that IPO7 activates PI3K/AKT-mTOR pathway to exert oncogenic function in CC cells by transporting GTF2I into the nucleus, which could provide clear information for the future of tumor treatment research." (PMID 34650978, 2021).
infection (4 papers, 2009 to 2025). The state of being infected such as from the introduction of a foreign agent such as serum, vaccine, antigenic substance or organism. "Nuclear import of the HIV-1 reverse transcription complex (RTC) is critical for infection of non dividing cells, and importin 7 (imp7) has been implicated in this process." (PMID 19193229, 2009). "Interestingly, although all three of the identified importins function in the basal nuclear shuttling of SIRT2, only IPO7 appears to function during infection with Listeria monocytogenes." (PMID 32042025, 2020). "Compared to a scrambled control, BKPyV-GFP infection was inhibited under IPO7 KD conditions, but MCPyV-GFP infection was again unaffected." (PMID 40445976, 2025).
bacterial infection (1 paper, 2020). "We show that multiple importins interact with and contribute to the basal nuclear shuttling of SIRT2 and that one of these, IPO7 is required for SIRT2 mediated H3K18 deacetylation in response to bacterial infection." (PMID 32042025, 2020).
IPO7 also shares sentences with these, for which no sentence is quoted: atherosclerosis (1 paper); breast (1); cervical intraepithelial neoplasia (1); co-infection (1); Epstein-Barr virus infection (1); gastrointestinal disease (1); glioma (1); heavy metal poisoning (1); lymph node metastasis (1); nervous system disorder (1); pancreatic adenocarcinoma (1); triple-negative breast carcinoma (1).